BRAF (B-Raf proto-oncogene, serine/threonine kinase)
Diseases named in the same sentence as BRAF in open-access papers (continued):
Sharing a sentence is not in itself a finding about the gene and the disease.
cancer (continued). "This review of the literature focuses on the biological mechanisms that link BRAF mutations with cancer, the role of such mutations in the context of GB, along with potential therapeutic opportunities, pitfalls and challenges." (PMID 34804975, 2021). "Cancer driver genes as BRAF and KRAS are usually found mutated in serrated polyps, along with MSI and CIMP (CpG island methylator phenotype)." (PMID 33672345, 2021). "The BRAF-V600E mutation can affect the molecular characteristics both in the primary cancers and LNMs." (PMID 34319022, 2021). "For instance, PIK3CA, KRAS and BRAF harbored 1457, 805 and 707 driver mutations from pan-cancer cohorts, respectively." (PMID 33179738, 2021). "BRAF is a predominant cancer driver gene, and it can be assumed that its mutation occurred earlier in oncogenesis." (PMID 34301805, 2021). "APC mutations were much more common in a minority of BRAF mutant cancers diagnosed at a younger age." (PMID 32384699, 2020). "Dabrafenib and trametinib are examined in this phase II basket trial in various cancers with BRAF V600E mutation, including BTC (NCT02034110)." (PMID 32100259, 2020). "For RAF research, the early spotlight on CRAF was shifted to BRAF after the discovery in 2002 that BRAF mutations (especially BRAFV600E) were dominant in cancer." (PMID 31941155, 2020). "For example, BRAF class III mutations such as BRAF D594G, G466V, G596R, G466E mutations which were predicted to be inactive by our system but are known cancer drivers." (PMID 32144301, 2020). "This protective function of NRF2 is the primary cause for therapy resistance in cancer as anti-cancer agents such as BRAF inhibitors also induce NRF2-dependent antioxidative response." (PMID 32477956, 2020). "Of note, the oncogenic contribution of mutated BRAF gene varies between cancer types, justifying significant differences in clinico-pathological features, prognostic impact and therapy response among various malignancies." (PMID 32015690, 2020). "The RAS-RAF-MEK-ERK pathway is altered in ~40% of all human cancers, mainly due to mutations in BRAF (~10%) and its upstream activator RAS (~30%)." (PMID 32046099, 2020). "Cancers with a truncating APC mutation occurred at an average age that was >10 years lower than the wider cohort of BRAF mutant cancers." (PMID 32384699, 2020). "We used Sanger sequencing to orthogonally validate the presence of WNT16 hotspot mutations in BRAF mutant cancers (n = 79) and identified frameshift mutations in 20.2% (16/79) of cancers." (PMID 32384699, 2020). "HER2 and BRAF mutation are important for clinical treatment and prognosis evaluation in cancer patients." (PMID 32095377, 2020). "As described in this review, cancer precision medicine based on driver mutations has accelerated the emergence of BRAF-mutated CRCs from basic research to clinical practice." (PMID 33152998, 2020). "Since genetic alterations of RTKs in cancers have been extensively reviewed in recent years, here we focus on oncogenic mutations of Ras and BRAF." (PMID 32807225, 2020). "The first evidence of an association between BRAF gene mutations and human cancers dates back to 2002." (PMID 33260892, 2020). "We recently assessed a series of 80 BRAF mutant cancers and identified truncating APC mutation in 11% of these cancers." (PMID 32384699, 2020). "Of all WNT signaling regulators assessed in this study, 110 were significantly differentially mutated between BRAF mutant and wild type cancers." (PMID 32384699, 2020). "BRAF mutations were first found in human cancers in 2002, and over 40 kinds of BRAF mutations have been identified since then." (PMID 32722429, 2020).
cancer (continued). "BRAF, which is well-known in cancer, as it is a major target of genetic mutations in tumorigenesis, has the highest activity among three isoforms, likely by virtue of its constitutively-phosphorylated NTA motif." (PMID 31941155, 2020). "The cancer precision medicine era became a tailwind in raising awareness of the significance of BRAF-mutated CRC in clinical practice." (PMID 33152998, 2020). "The prevalence of BRAF mutations was statistically significantly different by mutation assessment method in left‐sided cancers (P = .001) and among study country (P = .041) and median length of follow‐up (P = .007) among right‐sided cancers." (PMID 31856410, 2020). "The percentage of BRAF gene mutations has been reported in 15% of all human cancer types and in approximately 10% of CRC." (PMID 32899322, 2020). "AHNAK2 expression is significantly high in patients with an advanced cancer stage, an advanced T classification, lymph node metastasis, and increased BRAF mutations, showing a positive correlation with PTC progression." (PMID 32966238, 2020). "BRAF, a member of the raf family of serine/threonine protein kinases, has been shown to be mutated and constitutively activated in ~7% of all cancers." (PMID 32231639, 2020). "Mutation of the BRAF proto-oncogene is linked to a variety of cancers and it is used as a prognostic tool and therapeutic target." (PMID 32054005, 2020). "This study aimed to evaluate the sensitivity and specificity of a PCR-based novel technique for the detection of BRAF mutation in early stages of the cancer." (PMID 33247675, 2020). "Generally, BRAF mutations are more frequently associated with human cancer than ARAF and CRAF alterations." (PMID 33260892, 2020). "The mitogen-activated protein kinases/extracelluar signal-regulated kinases pathway is involved in cell growth and proliferation, and mutations in BRAF have made it an oncogene of interest in pediatric cancer." (PMID 33063010, 2020). "High sensitivity and specificity levels of QUASA-qPCR method can improve diagnostic accuracy for BRAF mutation testing in patients at early stages of cancers and help stratify the appropriate choice of treatment." (PMID 33247675, 2020). "We have shown that 48% of BRAF mutant cancers mutate at least one member of the B-catenin destruction complex." (PMID 32384699, 2020). "This review summarizes mechanisms of resistance to approved MAPK-targeted therapies in BRAF-mutated cancers and discusses novel preclinical approaches to overcoming resistance." (PMID 32411231, 2020). "Hotspots, recurrently mutated DNA positions in cancer, are thought to be oncogenic drivers because random chance is unlikely and the knowledge of clear examples of oncogenic hotspots in genes like BRAF, IDH1, KRAS and NRAS among many other genes." (PMID 32386297, 2020). "Deregulation of these processes by oncogenic BRAF has been implicated in different mechanisms underlying cancer development and progression." (PMID 32879641, 2020). "As for the other cancer types, the vast majority of BRAF mutations occur in codon 600 (exon 15 p.V600E)." (PMID 33260892, 2020). "Mutations in KRAS or BRAF genes appear to play an important role in the regulation of metabolic reprogramming in multiple cancers, including CRC." (PMID 32231083, 2020). "Still, unfortunately, the cancers commonly acquire other pro-survival mutations compensating for the depletion of BRAF activity and causing resistance to treatment." (PMID 32531927, 2020). "Recently, Hsp90 inhibitors were shown to prevent development of resistance to RAF inhibitors on BRAF(V600E)-harboring cancers in clinical trials, even though the underlying mechanism were too complicated to pinpoint a single molecule." (PMID 31941155, 2020).
cancer (continued). "In cancer genomes, BRAF is a major target of oncogenic mutations and a single-point mutation, and V600E represents >90% of events, while mutations in CRAF, ARAF, and KSRs are much less and have been detected in decreasing order of frequency." (PMID 31941155, 2020). "Developing active, molecularly targeted agents against mutated BRAF has been a major success story of the precision-cancer movement." (PMID 33216832, 2020). "RAF kinases are the first discovered RAS effectors and comprise three isoforms ARAF, BRAF, and CRAF of which BRAF is found often mutated in nearly 7% of human cancers." (PMID 31541179, 2020). "The probability of truncating APC mutation occurring in a BRAF mutant cancer decreases markedly with age from ~60% in patients diagnosed at age 40, to <10% of patients diagnosed at >90 years of age (Logistic Regression p = 3.74 × 10−7)." (PMID 32384699, 2020). "The different cancer histology was associated with a marked reduction of cell proliferation of BRAF FOXE1+/− cancers, as determined by immunohistochemistry (IHC) for Ki-67, compared to BRAF FOXE1+/+." (PMID 33375029, 2020). "WNT16 is a competitive inhibitor of canonical WNT and the mutation of WNT16 is common in BRAF mutant cancers." (PMID 32384699, 2020). "Vemurafenib, in combination with an MEK inhibitor, appeared to be promising in cancers harboring BRAF V600 mutations." (PMID 32423017, 2020). "In the database used here, there are more than 500 patients across diverse cancers reporting the BRAF V600 mutation." (PMID 32386297, 2020). "This is likely due to the increased frequency of MSI in BRAF mutant cancers, and the high frequency of the mutations in highly penetrant APC gene in BRAF wild type cancers, reducing the selective pressure on other WNT regulators." (PMID 32384699, 2020). "The relevance of BRAF as a new predictive marker lies in the fact that cancer patients harboring this mutation show poor response rates to conventional therapies." (PMID 33260892, 2020). "A limited number of patients included in the study had co-expressing tumors (BRAF V600E mutations and PD-L1 > 50% of cancer cells)." (PMID 32516941, 2020). "Sorafenib has previously demonstrated efficacy in both BRAF wildype and BRAF mutated cancer cell lines." (PMID 33014851, 2020). "The ROAR study is a basket trial with a total of nine cohorts, involving 178 patients harboring rare cancers with BRAF V600E mutations." (PMID 32384640, 2020). "These cancers are extremely aggressive and the survival of patients with both BRAF and APC mutation is poor (12% 5-year survival)." (PMID 32384699, 2020). "Many drugs are developed for commonly occurring, well studied cancer drivers such as vemurafenib for BRAF V600E and erlotinib for EGFR exon 19 mutations." (PMID 32144301, 2020). "The RAS-RAF-MEK-MAPK pathway is altered in ~40% of all human cancers, mainly due to mutations in BRAF (~10%) and its upstream activator RAS (~30%)." (PMID 33327491, 2020). "With another MEKi, clinical response to the BRAF inhibitor, dabrafenib, has been demonstrated thus far clinically in 20% women with BRAF V600E mutated low-grade carcinomas." (PMID 32679669, 2020). "Mutations of KRAS, NRAS, BRAF, and other components of the cascade are well-known in several cancers, including gastrointestinal, pulmonary, and skin malignancies, and represent the substrate for the targeted therapies currently in use." (PMID 30743998, 2019). "The involved network checks and balances can only be appropriately modeled in sufficient complex models to understand and treat cancer-specific differences; here exemplified by the failure of therapeutic success of vemurafenib in case of BRAF mutation in CRC." (PMID 31861874, 2019).
cancer (continued). "The BRAF (V600E) mutation is found in several human cancer, causing an increase of cell proliferation due to a modification of the ERK/MAPK-signal cascade." (PMID 31762942, 2019). "Correlation with cancer genomic data in 28 LUAD cell lines identified BRAF mutations located in or near the highly conserved kinase domain as strongly associated with resistance to DNA damage." (PMID 31723142, 2019). "It is intriguing that even though BRAF mutations are common in canine InvUC and that different molecular drivers are more common in human InvUC, the cancer in both species converges into a disease possessing the same molecular subtypes." (PMID 32039002, 2019). "Next generation sequencing (NGS) has been shown to have high accuracy and sensitivity in simultaneously analyzing cancer-associated genes including BRAF." (PMID 31810221, 2019). "Due to its multitude of variants, its significant alteration frequency in several cancer types and the variable clinical efficacy of drugs that target it, BRAF is a model oncogene to study molecular classification-based heterogeneity." (PMID 31723142, 2019). "Previous studies commonly reported that mutations in oncogenes such as KRAS, PIK3CA, BRAF were associated with clinical outcomes in various cancers." (PMID 30871151, 2019). "Research into the epigenetic mechanisms of BRAF dependency or escape from MAPK pathway dependency in BRAF-mutated cancers is still in its infancy." (PMID 31581557, 2019). "The vast majority of non-V600E mutations in BRAF occur at very low frequencies within and across cancer types." (PMID 31723142, 2019). "The patterns of somatic copy-number alterations across the three cancers showed that only SKCM tumors had significantly more focal amplifications (7q34) targeting BRAF, further supporting this association." (PMID 31723142, 2019). "We conclude with a discussion of potential therapies with epigenetic inhibitors alone or in combination with MAPK inhibitors to effectively target therapy-resistant BRAF-mutated cancers." (PMID 31581557, 2019). "The remarkable responses seen in patients with BRAF-mutated cancers have attracted attention in the field of neuro-oncology." (PMID 31466300, 2019). "Further investigation of the described co-desensitization events in other BRAF mutated cancer populations are needed to increase the relevance of the present findings for clinical purposes." (PMID 30631106, 2019). "These therapies, however, generate variable cellular and clinical outcomes in BRAF-mutated cancers that originate in distinct tissue types." (PMID 31581557, 2019). "BRAF (v-raf murine viral oncogene homolog B1), in particular, has been implicated as an oncogene in many different cancers." (PMID 31466300, 2019). "We found that the CCF of the BRAF variants varied significantly on the basis of cancer type, with ~9% of analyzed LUAD containing BRAF variants that were clonal compared to >80% of SKCM." (PMID 31723142, 2019). "We then attempted to address the overall frequency of rare, non-V600E BRAF mutations in human cancer." (PMID 31158244, 2019). "Similar types of point mutations were described in different cancers, supposing the contributive role of radiation exposure (BRAF, MAPK38, RAS)." (PMID 31480731, 2019). "The anti-BRAF V600E (VE1) antibody is currently used to evaluate the BRAF V600E mutation status in various cancers including CRC." (PMID 29127628, 2019). "Mutations in BRAF induce uncontrolled and persistent activation of this kinase-signaling pathway, causing over-proliferation of cancer cells." (PMID 31312183, 2019). "The effect of BRAF mutation on the secretion of chemokines was also investigated in human cancer patients." (PMID 31762942, 2019).
cancer (continued). "It is now known that BRAF mutations occur in a wide-range of cancers, particularly those with RAS mutations." (PMID 31350469, 2019). "The discovery of BRAFV600E mutations in multiple cancers spearheaded efforts to target the mutated BRAF." (PMID 31581557, 2019). "Almost all were initially filtered as germline events, as many well-known actionable cancer mutations (e.g., BRAF V600E and KRAS G12C) are present in the dbSNP database and occurred at frequencies that fell within our exclusion criteria." (PMID 31262303, 2019). "While high-dose therapy has been beneficial to several cancer patients, many studies have indicated this clinical benefit was limited to patients having BRAF mutation." (PMID 30760304, 2019). "To quantitate these differences, we first calculated the median CCF of tumors with BRAF mutations across all three cancer types." (PMID 31723142, 2019). "Gangliogliomas harbor molecular deficiencies such as mutations in the B-rapidly accelerated fibrosarcoma (BRAF) gene, resulting in activation of a downstream signaling pathway and cancer development." (PMID 30984614, 2019). "Increased MAP/ERK kinase (MEK) activity is a feature of many cancers, and is often triggered by missense mutations in BRAF and NRAS, two upstream oncogenes and potent regulators of Ras/Raf/Mek/ERK signaling." (PMID 30838036, 2019). "Single-cell genomic characterization of CTCs across these cancer types have revealed highly heterogeneous BRAF status across CTCs, with disparities in BRAF mutations to the corresponding primary tumor." (PMID 31635038, 2019). "We identified 405 candidate BRAF variants by analyzing targeted and genome-wide screen data from a collection of 48,397 tumors representing 35 cancers deposited in COSMIC19." (PMID 31723142, 2019). "Amplification of the oncogenes ERBB2, CDK6, MDM2 affected dependency, as did point mutations in PIK3CA, KRAS, NRAS, VHL and BRAF, validating our approach to highlight genes with significance in cancer." (PMID 30803482, 2019). "While BRAF mutations are common in certain forms of human cancer, these mutations are rare in human InvUC." (PMID 32039002, 2019). "The identification of BRAF as a commonly mutated target in cancers has significantly altered the management of affected cancer types." (PMID 31723142, 2019). "Studies of adaptive responses in BRAF-mutated cancers have shown that these responses are remarkably diverse." (PMID 31581557, 2019). "For class II or III mutations, including BRAF-fusions, preclinical data and data in other cancers clearly support the inefficacy of type I RAF inhibitors." (PMID 31466300, 2019). "We first describe the role of the BRAF kinase, its oncogenic mutations in cancer, and discuss the range of therapies that target BRAF-related malignancies." (PMID 31581557, 2019). "A kinase-impairing BRAF mutation (D594N) was detected in 6.8% of the cancer cell fraction in ctDNA at BL and this increased to 37.4% at PD in C1030." (PMID 31287991, 2019). "The RAS-RAF-MEK1/2-ERK1/2 signalling pathway is deregulated in a variety of cancers due to mutations in pathway components, most notably BRAF and the RAS isoforms." (PMID 35582726, 2019). "Sorafenib was the first RAF inhibitor to enter clinical trials, which occurred prior to the discovery of BRAF mutations in cancer." (PMID 30975211, 2019). "The growth patterns generated from the KRAS and BRAF mutated cells in 3D cultures revealed a resemblance to the putative anoikis-resistant subpopulations in actual carcinomas, including micropapillary structures and solid tumor cell islands." (PMID 31545494, 2019). "In 3D cultures, Caco-2 cells transfected with mutated KRAS or BRAF formed multicellular structures analogous to anoikis-resistant subpopulations in actual carcinomas, and serve as an in vitro model for anoikis resistance." (PMID 31545494, 2019).